U1 (U1 spliceosomal RNA )
Synonyms: LOC124905061
Gene: Small nuclear RNA gene on chromosome 21 (9,646,825 to 9,647,000, forward strand). Ensembl gene ENSG00000275631.
Gene Ontology:
Molecular function: pre-mRNA 5'-splice site binding
Biological process: mRNA 5'-splice site recognition
Cellular component: U1 snRNP
Homologues: Orthologues: chimpanzee U1 (99% identical), macaque U1 (91% identical), pig U1 (67% identical), rat U1 (62% identical), guinea pig U1 (61% identical), mouse Gm25115 (53% identical). Paralogues in human: U1 (100% identical), RNU1-51P (98% identical), RNU1-1 (76% identical), RNU1-2 (76% identical), RNU1-27P (76% identical), RNU1-28P (76% identical), RNU1-3 (76% identical), RNU1-4 (76% identical), RNU1-89P (76% identical), RNVU1-18 (76% identical), RNVU1-29 (76% identical), U1 (76% identical), and 134 more.
Diseases named in the same sentence as U1 in open-access papers:
U1 is named in the same sentence as 26 diseases in open-access papers, as found by Europe PMC text mining. Sharing a sentence is not in itself a finding about the gene and the disease. The quoted sentences say what the papers report.
mixed connective tissue disease (9 papers, 2008 to 2026). Mixed connective tissue disease (MCTD) is a rare autoimmune disorder that is characterized by features commonly seen in three different connective tissue disorders: systemic lupus erythematosus, scleroderma, and polymyositis. "This assessment can be extended to include the search for anti-ribonucleoprotein U1 (U1-RNP) antibodies for the diagnosis of mixed connective tissue disease (MCTD), which shares clinical characteristics with SLE, RA, and SSc." (PMID 41602963, 2026). "Mixed connective tissue disease (MCTD) is characterized by a combination of features of systemic sclerosis, systemic lupus erythematosus, and dermatomyositis associated with a high titer of anti-U1 ribonucleoprotein antibodies." (PMID 38850285, 2024). "Mixed connective tissue disease (MCTD) is a rare condition that is distinguished by the presence of specific U1-RNP antibodies." (PMID 33430976, 2021). "Anti-U1 RNP antibodies are present in approximately 25% of SLE patients, but high levels of these antibodies are also found in patients with mixed connective tissue disease." (PMID 36325322, 2022). "Mixed connective tissue disease (MCTD) is a systemic autoimmune syndrome characterized by the presence of high titers of serum antibodies against small nuclear ribonuclearproteins (U-snRNPs), in particular against U1 small nuclear RNP polypeptide (U1 snRNP)." (PMID 18275618, 2008).
systemic lupus erythematosus (6 papers, 2016 to 2026). An autoimmune multi-organ disease typically associated with vasculopathy and autoantibody production. "The detection of elevated blood levels of U1 antigen and circulating autoantibodies against U1 nuclear antigen are held to be the hallmark of systemic lupus erythematosus." (PMID 32085663, 2020). "As mentioned in the Study sample section, anti-U1 RNP antibody is occasionally observed in patients with SSc and systemic lupus erythematosus, and chronic interstitial pneumonitis as a complication of systemic lupus erythematosus is rare." (PMID 27564852, 2016).
scleroderma (4 papers, 2011 to 2024). Scleroderma is a rare autoimmune connective tissue disorder characterized by abnormal hardening of the skin and, sometimes, other organs. "Children with overlap syndrome (positive anti-U1 RNP, anti-U2 RNP or anti-PM-Scl), Systemic Lupus or Scleroderma were excluded." (PMID 37828536, 2023).
myositis (2 papers, 2017 to 2022). "Anti-PM/Scl, anti-Ku, anti-Ro, anti-La, anti-U1-RNP, and anti-U3-RNP are the most common myositis-associated antibodies and may be found in 20% of patients with myositis." (PMID 35147864, 2022).
congenital myasthenic syndrome (1 paper, 2021). Congenital myasthenic syndrome (CMS) is a group of genetic disorders of impaired neuromuscular transmission at the motor endplate characterized by fatigable muscle weakness. "In addition, U1 snRNP is also reported to be associated with other diseases, such as autoimmunity connective tissue disease (MCTD), systemic lupus erythematosus, congenital myasthenic syndrome (CMS) and others." (PMID 34568424, 2021).
endothelial dysfunction (1 paper, 2025). In vascular diseases, endothelial dysfunction is a systemic pathological state of the endothelium (the inner lining of blood vessels) and can be broadly defined as an imbalance between vasodilating and vasoconstricting substances produced by (or acting on) the endothelium. "U1 RNP immune complex, IFN-I response, endothelial dysfunction/ vasculopathy, fibroblast activation." (PMID 41465549, 2025).
motor neuron disease (1 paper, 2018). "Together, these data reveal an extensive association between the RNAP II/U1 snRNP machinery and motor neuron disease-causative proteins." (PMID 30398641, 2018).
osteoporosis (1 paper, 2025). A condition of reduced bone mass, with decreased cortical thickness and a decrease in the number and size of the trabeculae of cancellous bone (but normal chemical composition), resulting in increased fracture incidence. "This prompts us to suggest a thorough osteoporosis check-up in patients with high CRP, LN, or U1-RNP-antibodies." (PMID 40722203, 2025).
pulmonary arterial hypertension (1 paper, 2022). Pulmonary arterial hypertension (PAH) is a group of diseases characterized by mean pulmonary artery pressure >20 mmHg and elevated pulmonary arterial resistance leading to right heart failure. "A total of 10 studies contained statistics of the number of anti-U1 RNP antibody-positive patients in the CTD-PAH group and the connective tissue disease without pulmonary arterial hypertension (CTD-no PAH) group, respectively." (PMID 36614817, 2022).
connective tissue disease (6 papers, 2011 to 2023). "A subset of patients may also display overlap syndromes with other connective tissue diseases (e.g., systemic lupus erythematosus and polymyositis), and be variably associated with anti-Ku, PM-Scl75 or anti-U1-ribonucleoprotein antibodies." (PMID 35847779, 2022). "However, it should be noted that anti-U-1 RNP may be positive in other connective tissue diseases also." (PMID 32411251, 2020). "Because of the cooccurrence of POTS and Raynaud phenomenon, to evaluate connective tissue diseases, ANA, anti-ds DNA, anti-SCL70, and anti-U1-RNP antibodies results were assessed and no diagnosis of connective tissue disease was determined." (PMID 27413567, 2016).
vasculopathy (2 papers, 2022 to 2025). "Despite the fact that the exact role of the anti-U1 RNP antibody in CTD-PAH pathogenesis remains unclear, it is predicted that this antibody may contribute to the PAH development by participating in vasculopathy." (PMID 36614817, 2022).
U1 also shares sentences with these, for which no sentence is quoted: systemic sclerosis (3 papers); Arthritis (2); overlap syndrome (2); COVID-19 (1); dermatomyositis (1); hematologic disorder (1); inflammatory idiopathic myopathies (1); interstitial lung disease (1); neonatal lupus erythematosus (1); Oral ulcer (1); polymyositis (1); Primary Sjogren's syndrome (1); rheumatoid arthritis (1); sacroiliitis (1); vasculitis (1).